MGMT (O-6-methylguanine-DNA methyltransferase)
Diseases named in the same sentence as MGMT in open-access papers (continued):
Sharing a sentence is not in itself a finding about the gene and the disease.
tumor (continued). "Based on the final selected variables, age of diagnosis, KPS score, MGMT-promoter methylation status, extent of resection, use of corticosteroids, and location of the tumor in the brain are the significant predictors of OS for males." (PMID 34761331, 2021). "Our results suggest the decreased PCr/Pi ratio in patients with EGFR amplified or MGMT methylated tumor." (PMID 34298788, 2021). "Unfortunately, MGMT can also protect tumor cells by the same process and neutralize the cytotoxic effects of agents like TMZ." (PMID 33758290, 2021). "The mGBMs and uGBMs were matched in terms of sex, age, preoperative KPS, tumor size, Ki-67 indexes, and MGMT promoter methylation." (PMID 34646781, 2021). "The results indicated that age, tumor grade, IDH mutation, ATRX mutation, MGMT methylation, and immune score were significantly associated with OS (p < 0.001)." (PMID 34721530, 2021). "Similar results have been reported with alternative dosing schedules of temozolomide but activity is probably limited to patients with tumours with MGMT promoter methylation." (PMID 33293629, 2021). "Gene body methylation of MGMT was significantly lower in tumours in the subgroup T2 compared to tumours in the other groups (T1 and T3)." (PMID 33536587, 2021). "Subsequently, the clinical features of the three subtypes were investigated, including age, sex, tumor grade, IDH mutation status, 1p19q codeletion status, and MGMT promoter status in the TCGA and CGGA cohorts." (PMID 34815785, 2021). "In comparison to survival of patients following CR, OS was decreased in patients with residual tumor regardless MGMT methylation." (PMID 34185258, 2021). "Several parameters were identified as influential on patient survival, including tumor location, extent of resection, age at date of diagnosis, O6-methylguanine-DNA methyltransferase (MGMT) promoter methylation, and clinical performance." (PMID 34926307, 2021). "The DNA-repair enzyme O6-methylguanine-DNA methyltransferase (MGMT) impairs the killing of tumor cells by alkylating agents chemotherapy." (PMID 35008238, 2021). "Analyses of PFS and OS using Cox proportional hazard modeling with KPS, MGMT promoter methylation status, geographic region, age, tumor location, and resection status as covariates supported the primary findings in patients who were ≥65 years of age." (PMID 34692470, 2021). "ROC-derived cutoffs of 31 months for the duration between diagnosis and TMZ initiation, low-to-intermediate MGMT positivity (40% tumor cells), and MGMT h-score of 80 all had a sensitivity exceeding 80% and a specificity exceeding 70% to predict response." (PMID 34975752, 2021). "Difference in recurrence-free interval was also statistically observed in patients with unmethylated MGMT promoter and treated with chemoradiotherapies (p-value = 0.031), by which they showed a late tumor recurrence (p-value = 0.016)." (PMID 34257620, 2021). "After stratifying patients whose MGMT promoters were hypermethylated, those with a tumor area <967.4 mm2 had an increased median OS of 38.0 months (95% CI: 23.8–52.2)." (PMID 33747971, 2021). "More researches need to conduct to identify the prognostic value of MGMT promoter methylation in tumor patients responding to alkylating agents." (PMID 33628188, 2020). "The marker of proliferation Ki-67 labeling index was ∼1%, and the fraction of MGMT immunopositive tumor cells was ∼1%." (PMID 33031279, 2020). "We observed that tumor purity was significantly enriched in IDH-mutant samples or MGMT-promoter-methylated samples (student’s t-test, P < 0.001, P = 0.024, respectively), which were associated with favorable prognosis." (PMID 32021566, 2020). "In hindgut NET cases, two cases had lower GLUT2 and one lower MGMT status in the metastatic lesions with higher Ki-67 LI compared to those at primary tumor site." (PMID 33287738, 2020).
tumor (continued). "The wide variability in MGMT levels and post-translational modification of 22 different GBM tumor slices can also be observed by comparing MGMT phosphorylation to total MGMT levels." (PMID 32075134, 2020). "Methylation of the MGMT promoter leads to low expression of MGMT and inactivation of the repair protein, rendering tumor cells more sensitive to effects of alkylating agents." (PMID 32957941, 2020). "Altogether, MGMT protein provides protection of normal cells from exogenous carcinogens and tumor cells from chemotherapeutic agents." (PMID 32841306, 2020). "The marker of proliferation Ki-67 labeling index was ∼2%, and the fraction of MGMT immunopositive tumor cells was ∼60%." (PMID 33031279, 2020). "PRFP19 methylation was associated with survival in the combined analysis and in particular in MGMT promoter unmethylated, therefore, mainly temozolomide resistant, tumors and retained significance after controlling for tumor purity." (PMID 32991787, 2020). "Tumor MGMT methylation status was assessed for seven patients, with methylated MGMT promoter present in four of the seven." (PMID 32508561, 2020). "MGMT also affected the chemotherapeutic effect of different tumor patients, but the results are controversial." (PMID 32141507, 2020). "In both the MGMT‐deficient and MGMT‐proficient cell lines, CS‐6 cotreatment with TMZ notably led to a more pronounced decrease in tumour growth than monotherapy." (PMID 31746080, 2020). "For those patients for whom both primary and recurrent tumor were available (4 out of 7), the MGMT rearrangements were detected only in the tumor relapse." (PMID 32753598, 2020). "This likely reflects favorable tumor biology and suggests that MGMT remains an important prognostic, but less important predictive, biomarker." (PMID 31756059, 2020). "The most extensively investigated epigenetic mark in GBM is the methylation of the MGMT gene promoter, which is an independent prognostic factor for favorable tumor biology and a beneficial predictor of response to TMZ and radiotherapy." (PMID 31376079, 2020). "He provided informed consent for sharing of assay results across trials under the Longitudinal Sample Collection and Tracking protocol at the NCI, allowing us to document epigenetic silencing of MGMT in his archival tumor tissue." (PMID 33216844, 2020). "An MRI-based end-to-end deep learning pipeline is designed for tumor segmentation and MGMT methylation status prediction in GBM patients." (PMID 33029531, 2020). "The inactivation of MGMT in tumor cells has been appreciated as a therapeutic target for sensitizing cells to O6-alkylating agents." (PMID 33628188, 2020). "The IDH status serves as prognostic prediction biomarkers in clinical, and the MGMT status can predict tumor sensitivity to temozolomide." (PMID 32984316, 2020). "Early detection of MGMT genetic rearrangements in patients under treatment would eventually predict early tumor recurrence and guide therapy decision in a subset of MGMT-methylated patients." (PMID 32753598, 2020). "What is clear from the data available to us is that patients harboring a tumor with a methylated MGMT promoter survive longer and likely respond more robustly to TMZ chemotherapy." (PMID 32083011, 2020). "Another important issue, the necessary proportion or volume of tumor cell content in the analyzed sample, needs to be resolved before it will be possible to establish an accurate and reproducible cutoff for MGMT testing." (PMID 32025325, 2020). "On the contrary, the addition of EGCG to non-tumor glial cell culture (GliaX) enhances MGMT expression by inhibiting the methylation of the MGMT promoter." (PMID 32075265, 2020). "Our study on MGMT methylation prediction shows that MGMT methylation correlates with high values of fractal texture features such as histogram entropy of mBm for tumor volume." (PMID 32111869, 2020).
tumor (continued). "To identify clinical characteristics of the three subtypes of diffuse glioma, we examined conventional clinical variables, including age, gender, tumor grade, IDH mutation status, 1p19q codeletion status, and MGMT promoter status in TCGA cohort." (PMID 33425739, 2020). "MGMT inactivation by epigenetic silencing through methylation of CpG islands in the promoter region correlates with the sensitivity of tumor cells to alkylating agents." (PMID 32841306, 2020). "The necessary tumor cell content in the analyzed tissue for correct assessment of tumor MGMT methylation status needs to be addressed." (PMID 32025325, 2020). "To date, however, TMZ single-agent anti-cancer activity has only been directly correlated with tumor MGMT promoter methylation status." (PMID 33216844, 2020). "Hypoxic tumor cells are genetically unstable and show increased expression of O6-methylguanine-DNA-methyltransferase (MGMT) expression, a DNA repair enzyme known to negate TMZ-induced DNA alkylation." (PMID 32549357, 2020). "Promoter methylation of this gene reduces MGMT protein expression and consequently decreases DNA repair and increases alkylating chemotherapy induced tumor death." (PMID 32477929, 2020). "MGMT contributes to the intrinsic and acquired resistance of tumor cells to TMZ through transcriptional induction and increased enzyme activity." (PMID 32899791, 2020). "As bevacizumab has limited clinical efficacy in GBMs, this study suggests that MGMT-promoter methylation is predictive of response to alkylating chemotherapy at tumor progression." (PMID 33375286, 2020). "After adjusting for WHO grade, ATRX, Ki67, and MGMT, the IDH1, TERT, and 1p/19q molecular groups were independently associated with tumor growth." (PMID 32388499, 2020). "In conclusion, miR-370 was detected for the first time to be downregulated in PCNSL tissues, significantly correlated with the TMZ resistance and functioned as a tumor suppressor in raji cells depending on MGMT status." (PMID 30712191, 2020). "Another molecular mechanism explored presently was the effect of the Mif/Tz treatment on MGMT, which is related to DNA repair in tumor cells." (PMID 33123485, 2020). "Methylation of MGMT promoter leads to low expression of MGMT and silence of repair protein, which makes tumor cells more sensitive to effects of TMZ." (PMID 32957941, 2020). "Patient age, gender, tumor location, tumor size, MGMT promotor methylation status, and extent of resection, along with receipt of radiotherapy, TMZ, and bevacizumab, were included in univariable analyses." (PMID 32219069, 2020). "We concluded that ex vivo ultrasonic tissue fragments can capture variability in molecular markers, such as MGMT gene promoter methylation in the tumor core." (PMID 32226940, 2020). "Capecitabine transforms into 5-FU in tumor tissues, and its metabolites can reduce the activity of MGMT, thus enhancing the effect of TMZ on DNA replication." (PMID 32132978, 2020). "The methylation of the MGMT promoter was assessed as part of the routine pathological work-up: 45.5% of the tumours were categorised as MGMT-methylated, while 54.5 % were stated as non-methylated." (PMID 32260145, 2020). "We next determined the relationship between MGMT gene expression and MGMT methylation level in the 4 cell lines and 4 tumor samples." (PMID 32563269, 2020). "In line with that model, we detected increased MMR protein expression in EGFRvIII+ cells and human tumor samples demonstrating increased MMR to be the reason for the increased TMZ sensitivity in MGMT-deficient cells and tumors." (PMID 32066879, 2020). "For instance, the GBM163 tumor slice showed very low levels of active MGMT but very high levels of the inactive, phosphorylated MGMT." (PMID 32075134, 2020).
tumor (continued). "The therapeutic efficacy of STZ has been reported to be influenced by the status of both glucose transporter 2 (GLUT2) and O6-methylguanine-DNA methyltransferase (MGMT) in tumor cells." (PMID 33287738, 2020). "The MGMT promotor methylation status of the resected tumor was documented in 52 cases, from which 32 patients were categorized as unmethylated." (PMID 33374196, 2020). "The study further shows that the size ratio between enhancing tumor and necrosis correlates significantly with un-methylated MGMT, which indicates that the high aggressive MGMT un-methylated LGG, the higher the values of the size ratio." (PMID 32111869, 2020). "We also analyzed the relationship between efficacy and MGMT status, number of relapse, tumor dissemination, tumor size, and bevacizumab use after progression." (PMID 33634023, 2020). "This study presents an MR-based deep learning pipeline for automatic tumor segmentation and MGMT methylation status classification in an end-to-end manner for GBM patients." (PMID 33029531, 2020). "Using our limited sample of patients with known MGMT methylation status (methylated n = 9, unmethylated n = 14), we analyzed the relationship between methylation status, tumor volumetric response, cycles of TMZ, and D/rho." (PMID 32218600, 2020). "MGMT DNA repair activity of tumor cells is believed to contribute to resistance of tumor cells from cytotoxic effects of alkylating agents." (PMID 32841306, 2020). "Patients with isocitrate dehydrogenase (IDH)-mutant or O6-methylguanine-DNA-methyltransferase (MGMT) promoter-methylated tumours had a significantly longer PFS and OS (both P < 0.001)." (PMID 32034446, 2020). "Higher expression of E2F7 was significantly linked with higher tumor grade (P < .001), wild type (WT) of IDH (P < .001) and unmethylation status of MGMT promoter (P < .001)." (PMID 32064771, 2020). "The tumor tissue pathological analysis revealed that MGMT promoter was hypermethylated, EGFR was amplified, and PTEN was deleted in the original tumor." (PMID 33390879, 2020). "If more than 11.7% of MGMT gene promoter were methylated, the tumor was determined as MGMT promoter hypermethylated." (PMID 32841306, 2020). "Changes in MGMT promoter methylation status during tumor progression have been observed only in a small subset of patients." (PMID 32753598, 2020). "In univariate analysis, supratentorial tumor location (p = 0.026), MGMT promoter methylation (p = 0.014), STR/biopsy (p = 0.0006) and adjuvant RT (p = 0.04) were significantly associated with shorter PFS." (PMID 31362435, 2019). "These tumors were both MGMT methylated and unmethylated tumors and presenting various tumor location, although involvement of the frontal and parietal lobes was dominating." (PMID 31921679, 2019). "MGMT methylation status was only available on 51% of patients, and of these 43% had methylated tumours." (PMID 31088401, 2019). "Another common alteration in GB is the promoter methylation of the MGMT gene, which occurs in 30–60% of all GB patients, although with certain heterogeneity within the tumor." (PMID 31505812, 2019). "In our series, both clinical (tumor location) and molecular (MGMT promoter methylation status) markers helped to stratify patients with STR/biopsy into favorable and unfavorable outcomes." (PMID 31362435, 2019). "The levels of MGMT autoantibodies decreased on the 30th day after operation, reaching preoperative levels, similar to those when tumor recurrence developed." (PMID 31210005, 2019). "In some tumor cells, the expression of O6-methylguanine-DNA methyltransferase (MGMT) can directly remove the alkyl group from O6-guanine, resulting in resistance to TMZ." (PMID 30925729, 2019). "This trial will also investigate the role of MGMT on tumor tissue and methylation of its promoter in blood (NCT02698410)." (PMID 31273555, 2019).
tumor (continued). "It has been reported that O6-BTG efficiently and rapidly inactivates MGMT in various tumors in vivo and in v vitro and significantly increases tumor sensitivity to TMZ." (PMID 32010632, 2019). "Lower expression of the DNA repair protein O6-methylguanine-DNA methyltransferase (MGMT) has been proposed to correlate with TMZ effectiveness and checking for the MGMT tumour status by immunohistochemistry prior starting treatment is recommended." (PMID 31847209, 2019). "Western blotting of GBM-PDX tumor lysate reveals differential expression of MGMT between tumor samples, which correlated with the activation of the PI3K-AKT axis across all primary-derived GBM-PDX tumor specimens, but not for recurrent GBM-PDX (GBM10)." (PMID 31726966, 2019). "Due to missing data for MGMT promoter methylation in five cases or tumor volume for one patient, a total of six patients had to be excluded." (PMID 31200581, 2019). "When the tumor reoccurs, we found that the anti‐MGMT‐02, anti‐MGMT‐07, and anti‐MGMT‐10 peptide autoantibodies coverage of peptide increased." (PMID 31210005, 2019). "One of the early mutations discovered was O6-methylguanine-DNA methyltransferase (MGMT) promoter silencing, which reduces tumor cells’ ability to repair DNA damage from alkylating agents such as temozolomide (TMZ)." (PMID 31207930, 2019). "Nevertheless, we tried to minimize a potential bias by applying multivariate survival analysis including known (GTR) and potential (e.g., MGMT promoter methylation status, tumor location, adjuvant RT) confounding factors." (PMID 31362435, 2019). "In GC cells, PGE2 induced DNMT3B expression and activity, leading to increased methylated cytosine (5mC) and promoter methylation of tumor suppressive genes (MGMT and CNR1)." (PMID 31534549, 2019). "The therapeutic efficiency of ACNU for tumors is dependent on the MGMT expression status in tumor cells." (PMID 30988834, 2019). "In conclusion, MGMT promoter methylation status and tumor location were identified as novel prognostic factors in adult PAs, pointing at distinct molecular subtypes and detecting patients in need of close observance and intensified treatment." (PMID 31362435, 2019). "His GBM tumor tissue demonstrated O6-methylguanine-DNA methyltransferase (MGMT) promoter methylation, wild-type isocitrate dehydrogenase 1/2 (IDH1/2) and amplification of the epidermal growth factor receptor (EGFR) gene." (PMID 30766509, 2019). "The MGMT promoter methylation status in the patient's tumor was determined and found to be high, compatible with a low MGMT enzyme activity, providing the basis for a positive treatment response to TMZ." (PMID 31044184, 2019). "Up to 33% of the GBM were described to be heterogeneous with different MGMT promoter methylation status in the intermediate part of the tumor compared to the peripheral and inner parts." (PMID 31766430, 2019). "Research reports that the MGMT promoter within tumor tissue can convert from un-methylated to methylated status between initial and recurrent GBM, and vice versa." (PMID 30766509, 2019). "It is effective in inducing cell death if the tumor lacks MGMT or expresses it at low level, i.e., < 30 fmol/mg protein." (PMID 30925722, 2019). "The isocitrate dehydrogenase (IDH) mutation status and methylation of the O-6-methylguanine-DNA methyltransferase (MGMT) gene promoter are established prognostic markers of GBM evaluated in patients’ tumor samples." (PMID 31200581, 2019). "This is also reflected by the fact that three out of four patients with tumor recurrence after GTR harbored MGMT promoter methylation." (PMID 31362435, 2019).